CYP27B1 (cytochrome P450 family 27 subfamily B member 1)
Diseases named in the same sentence as CYP27B1 in open-access papers (continued):
Sharing a sentence is not in itself a finding about the gene and the disease.
primary hyperparathyroidism (2 papers, 2024 to 2025). "We molecularly diagnosed mutations in CASR, KMT2D, GNAS, PRKAR1A, and CYP27B1, corresponding to cases with clinical diagnoses of isolated hypoparathyroidism/primary hyperparathyroidism, syndromic hypoparathyroidism, pseudohypoparathyroidism, acrodysostosis, and calcipenic rickets." (PMID 41155848, 2025).
Sepsis (2 papers, 2022). Sepsis is defined as life-threatening organ dysfunction caused by a dysregulated host response to infection. "Immunofluorescence results indicated that APS increased CYP27B1 protein expression and decreased CYP24A1 in rat kidneys, indicating that APS could effectively prevent renal cell apoptosis, reduce protein cast formation, and inhibit the occurrence of renal injury in rats with sepsis." (PMID 36338128, 2022).
skin melanomas (2 papers, 2014 to 2015). "Likewise, in our previous study, the absence of CYP27B1 protein in cutaneous melanomas was associated with shorter overall and disease-free survival." (PMID 25501638, 2015). "Previously we showed a negative correlation of vitamin D receptor (VDR) and CYP27B1 expression with progression, aggressiveness and overall or disease-free survivals of skin melanomas." (PMID 25334067, 2014).
uremia (2 papers, 2012 to 2022). A clinical syndrome associated with the retention of renal waste products or uremic toxins in the blood. "In fact monocytic baseline CYP27B1 expression is increased in uremia, probably reflecting the micro-inflammatory condition." (PMID 28197428, 2012). "On the other hand, elevated fibroblast growth factor 23 (FGF23) levels, may account, at least partly, for the dysregulation of monocytic CYP27B1 in uremia and, as such, may contribute to the high cardiovascular and infectious disease and immune system disorder in chronic renal failure." (PMID 28197428, 2012).
uveitis (2 papers, 2013 to 2016). An inflammatory process affecting a part of or the entire uvea. "The aim of this study was to investigate a possible association between the rs703842 A>G polymorphism of the CYP27B1 gene and HLA-B27-associated uveitis." (PMID 23614044, 2013).
acute myeloid leukemia (1 paper, 2020). Acute myeloid leukemia (AML) is a group of neoplasms arising from precursor cells committed to the myeloid cell-line differentiation. "In our recent study of acute myeloid leukemia (AML) cells, we observed significantly lower levels of CYP27B1 proteins within bone marrow (BM) cells when compared to non-AML controls." (PMID 32847594, 2020).
AIDS (1 paper, 2019). A syndrome resulting from the acquired deficiency of cellular immunity caused by the human immunodeficiency virus (HIV). "This pathway is of interest, as CYP27B1 may be influenced by processes occurring in the kidneys in MS and other AIDs." (PMID 30900415, 2019).
alopecia totalis (1 paper, 2024). Alopecia totalis is a form of alopecia areata, an inflammatory disease of the hair follicle, characterized by a complete loss of hair of the entire scalp which becomes glabrous. "Notably, loss of the VDR, but not CYP27B1, in mice and humans leads to alopecia totalis." (PMID 39321290, 2024).
anaplastic thyroid cancer (1 paper, 2022). "In anaplastic thyroid cancer, there was a tendency to more frequent negative results for CYP27B1 with increasing Ki67 or in cases with distant metastases." (PMID 36362448, 2022).
Arthritis (1 paper, 2016). Inflammation of a joint. "In this study, we demonstrated that CYP27B1 deficiency increased cumulative arthritis scores and levels of serous RFs and C-RP." (PMID 27763638, 2016). "Compared with WT CIA mice, body size was decreased; however, cumulative arthritis scores from 1 to 9 weeks after primary immunization, paw thickness, levels of rheumatoid factors (RFs) and C-reactive protein (C-RP) from serum increased significantly in vehicle-treated CYP27B1−/− CIA mice." (PMID 27763638, 2016).
autism (1 paper, 2012). Persistent deficits in social interaction and communication and interaction as well as a markedly restricted repertoire of activity and interest as well as repetitive patterns of behavior. "Genetic polymorphisms of cytochrome P450 enzymes have also been linked to autism, specifically CYP27B1 that is essential for proper vitamin D metabolism." (PMID 22898564, 2012).
carcinomas in situ (1 paper, 2010). "In fact, CYP27B1 was expressed in 55.8% of the preneoplastic lesions and this percentage is decreased in invasive tumours (44.6%), while carcinomas in situ display the highest value (66.4%) and these differences are statistically significant." (PMID 20831823, 2010). "The series of 189 tumours with both components (carcinomas in situ and the corresponding invasive tumour) allowed the evaluation of the expression of the VDR, CYP27B1 and CYP24A1 simultaneously in the two types of tumours." (PMID 20831823, 2010). "The results obtained show that the three proteins (VDR, CYP27B1 and CYP24A1) display a statistically significant correlation of expression between the two sections (carcinomas in situ and the matching invasive tumour)." (PMID 20831823, 2010). "We have used a cohort comprising normal breast, benign mammary lesions, carcinomas in situ and invasive carcinomas and assessed the expression of the VDR, CYP27B1 and CYP24A1 by immunohistochemistry." (PMID 20831823, 2010). "The main purpose of this work was to perform an immunohistochemical study of the expression of the VDR, CYP27B1 and CYP24A1 in a comprehensive series of human breast tissues comprised of normal breast, benign mammary lesions, carcinomas in situ and invasive breast carcinomas." (PMID 20831823, 2010).
cardiac arrhythmia (1 paper, 2025). Any disturbances of the normal rhythmic beating of the heart or MYOCARDIAL CONTRACTION. "For cardiac arrhythmias (n = 143 cases), significant associations were observed for CYP27B1 rs4646536 under the genotypic (p = 0.009), recessive (p = 0.002), and allelic (p = 0.047) models, as well as for CYP27B1 rs3782130 under the genotypic (p = 0.014) and recessive (p = 0.004) models." (PMID 40237935, 2025). "However, despite these limitations, our results remain robust after Bonferroni correction, confirming associations between CYP2R1 rs10741657 and CYP27B1 rs3782130 with general CVD risk, as well as CYP27B1 rs3782130 and CYP27B1 rs4646536 with cardiac arrhythmias." (PMID 40237935, 2025).
cervical adenocarcinoma (1 paper, 2023). An adenocarcinoma arising from the cervical epithelium. "The expression of CYP27B1 in SiHa cells is consistent with another study that detected CYP27B1 RNA semi-quantitatively in healthy cervical tissue, HeLa cervical adenocarcinoma cells, and cervical tumours." (PMID 36979850, 2023).
chronic hepatitis B (1 paper, 2017). "Genotype frequencies of DHCR7, CYP27B1, CYP2R1, GC and VDR in HBeAg-positive chronic hepatitis B patients treated with PegIFN for 48 weeks." (PMID 28296915, 2017).
chronic pancreatitis (1 paper, 2023). A chronic inflammatory process causing damage and fibrosis of the pancreatic parenchyma. "Finally, this study did not compare acute and chronic pancreatitis, which might affect VDR, CYP24A1, and CYP27B1 expression levels." (PMID 37808100, 2023).
cutaneous sarcoidosis (1 paper, 2025). "Glucocorticoid therapy inhibits granuloma formation and reduces CYP27B1 expression in granulomatous areas of cutaneous sarcoidosis." (PMID 41306174, 2025).
dementia (1 paper, 2022). Loss of intellectual abilities interfering with an individual's social and occupational functions. "Conversely, PD patients with white matter alterations and concomitant dementia had significantly fewer CYP27B1 positive astrocytes in the cortex, despite the total GFAP positive cells were unchanged." (PMID 35166042, 2022). "We observed that CYP27B1 expression in the frontal cortex white matter was significantly increased in patients with Lewy body pathology, but without white matter alteration or dementia." (PMID 35166042, 2022). "We found that the brains of PD patients without dementia have a threefold higher content of CYP27B1 positive astrocytes in the frontal cortex and do not have white matter degeneration, thus suggesting that vitamin D could exert its neuroprotective role through astrocytes." (PMID 35166042, 2022).
depression (1 paper, 2023). "Rats exhibiting depression-like symptoms demonstrated increased expression of CYP27B1, CYP24A1 and VDR in the hippocampus and elevated levels of 1,25 (OH)2D." (PMID 37404714, 2023). "Although no studies have investigated the relationship between CYP27B1 and PSD, animal studies have revealed that increased CYP27B1 expression is associated with depression." (PMID 37404714, 2023).
enamel hypoplasia (1 paper, 2023). "Three affected individuals are described in the present study with variants in CYP27B1, one of the individuals (P1) showed the complete and severe spectrum of disease with enamel hypoplasia and hypocalcemic seizures with early age of onset (4 mo of age)." (PMID 36692815, 2023).
end-stage renal failure (1 paper, 2025). "In macrophages, CYP27B1 activity is also suppressed by FGF23, and in serum from patients with end-stage renal failure, who have very high FGF23 concentrations, stimulated CYP27B1 expression and calcitriol synthesis are reduced relative to serum from healthy donors." (PMID 40565034, 2025).
endometriosis (1 paper, 2025). The growth of functional endometrial tissue in anatomic sites outside the uterine body. "It is unclear what this means for vitamin D function in endometriosis ovarian tissue, as higher CYP27B1 and VDR would be consistent with improved 25(OH)D conversion to 1,25(OH)2D and subsequent signalling." (PMID 39739404, 2025). "Reported studies have shown increased expression of the gene for 1α‐hydroxylase (CYP27B1) in ovarian tissue from women with endometriosis, although the extent to which any local synthesis of 1,25(OH)2D in this tissue could spill over into the general circulation is unclear." (PMID 39739404, 2025). "One study that assessed mRNA expression for various vitamin D‐related factors including VDR, CYP27B1 and the catabolic enzyme 24‐hydroxylase (CYP24A1) in ovarian tissues showed that women with endometriosis had higher expression of VDR, CYP27B1 and CYP24A1." (PMID 39739404, 2025).
enthesopathy (1 paper, 2023). "Because FGF23 overexpression is unlikely to be the only consequence of the PHEX mutation, ablation of both Cyp27b1 and Fgf23 in Hyp mice (C–/–F–/–/Hyp) will further elucidate if 1,25D- and FGF23-independent effects of the PHEX mutation influence XLH enthesopathy pathogenesis." (PMID 37490334, 2023). "Mice lacking Cyp27b1 or Hyp mice were treated with 1,25D starting early in postnatal development or after enthesopathy had already developed, to determine whether enhancing 1,25D action can prevent and/or attenuate BMP and IHH signaling in entheses." (PMID 37490334, 2023). "Analysis of entheses in mice null for both Cyp27b1 and Fgf23 (C–/–F–/–), which have normal serum calcium and phosphate levels when fed a rescue diet, will differentiate whether impaired 1,25D production due to high FGF23 levels or actions specific to FGF23 lead to XLH enthesopathy." (PMID 37490334, 2023).
Failure to thrive (1 paper, 2024). Failure to thrive (FTT) refers to a child whose physical growth is substantially below the norm. "A brief literature review of VDDR1A cases with CYP27B1 pathogenic variants clinically showed 59% failure to thrive/growth retardation, 38–41% delayed motor milestones/inability to walk, 13% poor feeding, 27% leg bowing, 16.5% seizure, and 13.6% fracture." (PMID 39452491, 2024).
Follicular Cyst (1 paper, 2021). Cyst due to the occlusion of the duct of a follicle or small gland. "In the ovary, CYP27B1 and CYP24A1 were found exclusively in the granulosa cells of healthy follicles with a lack of positive staining in follicular cysts." (PMID 33095902, 2021).
glaucoma (1 paper, 2024). Increased pressure in the eyeball due to obstruction of the outflow of aqueous humor. "Here, we also used variants in the CYP2R1, CYP27A1 and CYP27B1 genes for evidence of association with glaucoma." (PMID 39202443, 2024).
glioblastoma (1 paper, 2012). The most malignant astrocytic tumor (WHO grade IV). "Five moderate to high-level amplified genes in glioblastomas identified in this study, EGFR, PDGFRA, CDK4, MDM2 and CYP27B1, have also been previously reported, sometimes with co-amplification." (PMID 22691727, 2012).
glioma (1 paper, 2019). A benign or malignant brain and spinal cord tumor that arises from glial cells (astrocytes, oligodendrocytes, ependymal cells). "To further explore the role of the vitamin D metabolic pathway in glioma, we examined the expression of vitamin D receptors and CYP27A1 and CYP27B1, key enzymes involved in synthesis of 25(OH)D3 and 1α,25(OH)2D3 in glioma tissues." (PMID 30631035, 2019). "The expression of CYP27A1 is relatively low in high level glioma tissue, the expression of CYP27B1 is elevated in glioma tissues and increased significantly in grade IV glioma tissue." (PMID 30631035, 2019).
Granuloma (1 paper, 2025). A compact, organized collection of mature mononuclear phagocytes, which may be but is not necessarily accompanied by accessory features such as necrosis. "We report a case of renal sarcoidosis in which expression of 25-hydroxyvitamin D-1 alpha hydroxylase (CYP27B1) in epithelioid granulomas and multinucleated giant cells led to 1,25(OH)2D3 elevation, resulting in AKI." (PMID 41306174, 2025).
head and neck carcinoma (1 paper, 2023). A carcinoma that arises from the head and neck region. "A single study indicates that genes involved in the vitamin D metabolism pathway, CYP27B1 and CYP24B1, may also affect individual susceptibility to head and neck carcinoma." (PMID 37299554, 2023). "Another study examined the influence of genetic sequence variants (GSVs) in the vitamin D3 metabolism pathway, candidate-based GSVs, i.e., VDR, GC, CYP24A1, CYP27A1, CYP27B1, and CYP2R1, on overall survival (OS) and second primary cancer (SPC) in head and neck cancer patients." (PMID 37299554, 2023).
hepatocellular carcinoma (1 paper, 2024). A malignant tumor that arises from hepatocytes. "The interaction of MYL12B with MAFG-AS1 promotes the proliferation and migration of hepatocellular carcinoma cells, and CYP27B1 is a risk gene for malignant tumors and other chronic diseases." (PMID 39394698, 2024).
Hypercalciuria (1 paper, 2011). "In HHRH, CYP27B1 is actually upregulated, resulting in increased 1,25(OH)2D3 concentrations, and perhaps explaining the hypercalciuria." (PMID 21747952, 2011).
Infertility (1 paper, 2020). "As with Vdr (R270L) rats, administration of 25(OH)D3 exerted pronounced effects on Cyp27b1-KO rats, resulting in normalization of plasma calcium and PTH levels, osteogenesis, and infertility in females." (PMID 32231239, 2020).
interstitial nephritis (1 paper, 2020). Inflammation of the renal tubules and supporting tissues of the kidney. "CYP24A1 and CYP27B1 expression in the tubules is elevated in CKD patients with acute renal inflammation, ie, renal vasculitis or interstitial nephritis, and in adenine‐treated uremic rats with marked interstitial fibrosis, severe tubular dilatation, microcystic change, and foci of tubular atrophy." (PMID 32617522, 2020).
invasive carcinoma (1 paper, 2010). A carcinoma that is not confined to the epithelium, and has spread to the surrounding stroma. "In contrast, the stable levels of CYP27B1 throughout the transformation process, with only a small decrease in invasive carcinomas, may reflect a lower capacity to metabolize Vitamin D into its active form." (PMID 20831823, 2010). "CYP27B1 expression is slightly lower in invasive carcinomas (44.6%) than in benign lesions (55.8%)." (PMID 20831823, 2010).
ischemic stroke (1 paper, 2023). A stroke disorder caused by obstruction of blood flow to the brain, due to thrombotic (local blood clot formation) or embolic (due to a blood clot or other material traveling from another site) event. "Our findings suggest that the polymorphisms of VitD metabolic pathway genes VDR and CYP27B1 may be associated with PSD in patients with ischemic stroke." (PMID 37404714, 2023).
keloid (1 paper, 2025). An irregularly shaped, elevated mark on the skin caused by deposits of excessive amounts of collagen during wound healing. "Genetic variations in the CYP27B1 and CYP24 genes may also promote individual susceptibility to keloids, as differences in enzyme activity can alter vit D3 levels and thereby impact the regulation of fibroblast and immune cell activity." (PMID 39895409, 2025). "Reduced or abnormal expression of CYP27B1 in keloid tissue could lower vit D3 levels, whereas lower levels of CYP24 or selective inhibitors of CYP24 could slow down the metabolism of vit D3, potentially disrupting the pathways that help drive keloid formation." (PMID 39895409, 2025).
laryngeal carcinoma (1 paper, 2024). Carcinoma that arises from the laryngeal epithelium. "Through the expression of CYP24A1 and CYP27B1, laryngeal cancer cells can produce vitamin D3 metabolites 1,25(OH)2D3 and 24,25(OH)2D3 at biologically relevant levels." (PMID 38730587, 2024). "CYP27B1 expression showed higher levels in both laryngeal cancer cells than NRK-52E cells." (PMID 38730587, 2024).
leishmaniasis (1 paper, 2021). Infectious disease that is transmitted through the bite of hematophagous female phlebotomine sand flies. "However, results suggest that at the endpoint healthy animals have higher expression of β-defensin CBD103, while animals suffering leishmaniasis have higher expression of CYP27B1." (PMID 34398874, 2021).
liver fibrosis (1 paper, 2017). "Univariate analysis of HCV genotype 1 patients showed that age, liver fibrosis stage 0–1, CYP27B1 rs10877012 polymorphism, and DHCR7 rs12785878 polymorphism were related to SVR." (PMID 28415985, 2017).
lupus nephritis (1 paper, 2022). Glomerulonephritis in the context of systemic lupus erythematosus. "We collected and analyzed clinical data and found that the prevalence of lupus nephritis is higher while SLE is more active in patients with low mRNA expression of CYP27B1." (PMID 36326421, 2022). "Among SLE patients, the prevalence of lupus nephritis was higher in a subgroup with lower CYP27B1 mRNA expression than in a subgroup with normal CYP27B1 mRNA expression (41.07% vs. 14.28%, p = 0.028)." (PMID 36326421, 2022).
mastitis (1 paper, 2022). Inflammation of breast tissue during lactation or postpartum due to an obstructed duct or infection. "Additionally, a Streptococcus uberis (S. uberis) bovine mastitis model observed localized expression increased for CYP27B1 in milk CD14+ cells during active mastitis, while CD14- cells saw increased CYP24A1." (PMID 36144467, 2022).
metabolic acidosis (1 paper, 2022). "Metabolic acidosis is known to inhibit CYP27B1, the main enzyme that participates in calcitriol synthesis, although the influence of acidosis on circulating levels of vitamin metabolites D is controversial." (PMID 35268016, 2022).
nephritis (1 paper, 2022). Inflammation of renal tissue. "The expression of CYP27B1 in PBMCs may be related to SLE pathogenesis, disease activity, and nephritis." (PMID 36326421, 2022).
Nephropathy (1 paper, 2022). A nonspecific term referring to disease or damage of the kidneys. "In our ApoE KO mice with adenine-induced nephropathy, FGF23 was increased, and Vdr and Cyp27b1 mRNA levels were down-regulated in the kidney, providing evidence for impaired bone growth conditions." (PMID 36009040, 2022).
papillary thyroid carcinoma (1 paper, 2021). "Penna‐Martinez et al45 revealed that the rs10877012A/rs4646536T haplotype within the CYP27B1 gene might be protective against papillary thyroid carcinoma." (PMID 33058307, 2021).